INS (insulin)
Diseases named in the same sentence as INS in open-access papers (continued):
Sharing a sentence is not in itself a finding about the gene and the disease.
thyroid cancer (48 papers, 2011 to 2026). "Higher MD adherence has been associated with improvements in body weight regulation, insulin sensitivity, oxidative stress markers, and lipid profiles, contributing to reduced long-term cardiovascular and thyroid cancer risks." (PMID 41228493, 2025). "POM121C is a candidate gene for fasting insulin in genome-wide association studies and part of a gene signature involved in glycolysis in thyroid cancer." (PMID 38177114, 2024). "Elevated insulin resistance and heightened insulin levels in the bloodstream have been correlated with an augmented susceptibility to thyroid cancer." (PMID 37780617, 2023). "The possible effect of insulin therapy as a risk factor for thyroid cancer comes from pre-clinical data suggesting that insulin signaling is a key mediator in thyroid cancer cell growth." (PMID 38146457, 2023). "In conclusion, although pre-clinical data would support a role of insulin therapy as a risk factor for thyroid cancer, clinical data are still inconclusive." (PMID 38146457, 2023). "Only few clinical studies up to now evaluated the relationship between insulin therapy and thyroid cancer risk." (PMID 38146457, 2023). "An IR-B-dominant phenotype would presumably be more responsive to insulin and has been associated with a more differentiated phenotype in a number of different tissues, including adipocytes, hepatocytes, and in thyroid cancer." (PMID 27733843, 2016). "First, chronic elevated insulin levels observed in patients with DM may influence thyroid cancer risk, which was mediated by insulin receptors overexpressed in cancer cells and tissues." (PMID 36213272, 2022). "The chronically elevated circulating insulin levels associated with DM may influence thyroid cancer risk mediated by insulin receptors overexpressed by cancer cells." (PMID 24927125, 2014). "Both insulin and sulfonylurea may increase insulin level, but only the use of sulfonylurea showed a significantly higher risk of thyroid cancer." (PMID 23300866, 2012). "Therefore, the mechanisms leading to an increased risk of thyroid cancer during the early phase of sitagliptin use might have been counteracted by its long-term effect on the improvement of insulin resistance and inflammation." (PMID 27029076, 2016). "Metformin has been demonstrated to reduce the cell viability of thyroid carcinoma cells, blocking cell cycle progression and inducing apoptosis, reducing the insulin-stimulated cell proliferation of thyroid carcinoma cells and their cancer stem cells." (PMID 39199391, 2024). "Metformin can inhibit insulin-induced growth stimulation in differentiated and undifferentiated thyroid cancer and thyroid cancer stem cells, and these effects of metformin are closely related to insulin/IGF signaling and AMPK/mTOR pathways." (PMID 37773165, 2023). "A 2014 studies based on data from the reimbursement databases of all Taiwanese diabetic patients from 1996 to 2009 evaluated the incidence of thyroid cancer according to the use, duration and dosage of therapy with human insulin." (PMID 38146457, 2023). "Pioglitazone is an insulin sensitizer for type 2 diabetes with therapeutic effects in mouse models of thyroid cancer due to the fusion protein (PAX8-PPARg) present in 30% of thyroid cancer." (PMID 35327549, 2022). "Fixed-effect model was used to merge the WMD and pooled effect size is 1.24 (95% CI 1.08 to 1.40, P<0.00001), which showed that thyroid carcinoma patients have a higher level of fasting serum insulin than controls." (PMID 34550096, 2021). "Previous studies have reported that the level of fasting serum insulin is higher in thyroid carcinoma patients than controls." (PMID 34550096, 2021). "All the three subgroups show a significantly higher level of fasting serum insulin in the group of thyroid carcinoma." (PMID 34550096, 2021). "PID1, a gene that regulates the sensitivity of fat and muscle cells to insulin signals, has been reported as a feature gene in several cancers, including thyroid cancer." (PMID 32299435, 2020).
thyroid cancer (continued). "However, in thyroid cancer, insulin at supra-physiological concentrations promotes thyroid cell proliferation." (PMID 36975518, 2023). "Existing research posits that metabolic hormone imbalances, including insulin and leptin, may play a role in the pathogenesis of thyroid cancer." (PMID 37780617, 2023). "In addition, metformin significantly reduces the effect of insulin on differentiated human thyroid cells, mesenchymal thyroid cancer cells, adriamycin-resistant thyroid cancer cell lines and thyroid cancer stem cells by growth stimulation." (PMID 37773165, 2023). "In accordance with our results, an increase of circulating levels of insulin is correlated to an increase of thyroid proliferation, and increased expression of insulin receptors has been described in cancers, including thyroid carcinomas." (PMID 34381564, 2021). "Random-effect model was used to merge the weighted mean difference value of fasting serum insulin level and the pooled effect shows that the level of fasting serum insulin is higher in patients with thyroid carcinoma than those of controls (1.88, 95% CI 0.87 to 2.90, P=0.0003)." (PMID 34550096, 2021). "Metformin diminishes growth stimulation by insulin and inhibits growth of thyroid cancer in vitro." (PMID 22778714, 2012). "Factors related to cardiovascular risk and insulin sensitivity seem to be related to the increase in the number of thyroid cancer (TC) diagnosis, but there is a lack of studies to corroborate these hypotheses." (PMID 40662255, 2025). "In addition, metformin antagonized the growth-stimulating effects of insulin, inhibited clonal cell growth, reduced thyroid cancer spheroid formation and enhanced the antimitotic effects of chemotherapeutic agents (doxorubicin and cisplatin) on anaplastic thyroid cancer (ATC) cells." (PMID 37773165, 2023). "mTOR pathway targets are activated in thyroid cancer, and metformin may also inhibit the growth, migration and mesenchymal transition of thyroid cancer cell lines through the mTOR pathway other than the insulin pathway." (PMID 37773165, 2023). "In our study, the mean HOMA-IR (P = 0.005) and insulin (P = 0.006) levels were higher in the DTC group than in the control group, and multivariate binary logistic regression analysis showed the increased HOMA-IR level is associated with the development of thyroid cancer." (PMID 35255873, 2022). "However, to our knowledge, there has been no human study directly confirming the association between insulin exposure and thyroid cancer." (PMID 22778714, 2012). "With respect to thyroid cancers, specifically, TSH was shown to stimulate the expression of the glucose transporter GLUT2 on β-cells, leading to increased glucose-stimulated insulin secretion in vivo and in vitro." (PMID 35158824, 2022). "Some recent in vitro studies suggested that metformin may inhibit the growth of thyroid cancer cells through inhibition of the mammalian target of rapamycin (mTOR) pathway by activating the AMP-activated protein kinase (AMPK) or by diminishing the growth stimulation by insulin." (PMID 25303400, 2014). "In 6 studies using malignant cells (MCF-7 cells, Colo-357 cells, T47 D cells, MDA-MB-231 cells, T24 cells, thyroid cancer FTC-133 cells, insulin glargine displayed similar mitogenic potency as compared to human insulin." (PMID 21714872, 2011). "These anticancer effects are thought to be mediated through interference with insulin/IGF signalling and modulation of the AMPK/mTOR pathway, which inhibits unchecked cell cycle progression, induces apoptosis in thyroid cancer cells, and reduces colony formation and migration." (PMID 40055991, 2025). "When specifically evaluating thyroid cancer, a significant difference between insulin users versus non-users was observed only in female patients." (PMID 38146457, 2023). "The PPAR signaling pathway, the insulin signaling pathway, and the mTOR signaling pathway may be the critical pathways for controlling TNFRSF12A in thyroid cancer." (PMID 36142828, 2022).
thyroid cancer (continued). "In conclusion, the level of fasting serum insulin in thyroid carcinoma patients is statistically significant increased compared to persons without thyroid carcinoma." (PMID 34550096, 2021). "Importantly, not all studies support a beneficial effect of insulin sensitizing drugs on thyroid cancer." (PMID 35158824, 2022). "The mechanisms for this association are not clear; however, IGF-1 receptors are overexpressed on thyroid cancer cells and may be activated by chronically elevated levels of circulating insulin, leading to cell proliferation." (PMID 32392279, 2020). "The effect of insulin on leptin expression in thyroid cancer has not been studied." (PMID 23425972, 2013).
Cushing syndrome (46 papers, 2011 to 2026). Cushing's syndrome (CS) encompasses a group of hormonal disorders caused by prolonged and high exposure levels to glucocorticoids that can be of either endogenous (adrenal cortex production) or exogenous (iatrogenic) origin. "Mutated genes in TETs were enriched in several hormone-associated pathways such as insulin secretion; Cushing syndrome; parathyroid hormone; and thyroid hormone, as well as multiple classical tumor-associated pathways, including cAMP, Notch, PI3K-Akt, and WNT signaling pathway." (PMID 41388389, 2025). "These pathways remained significantly altered even after FDR correction, with Cushing syndrome, aldosterone synthesis and secretion, and insulin secretion showing P.adjust < 0.05, and the remaining pathways displaying P.adjust < 0.08." (PMID 41388389, 2025). "We found that genetic alterations in TETs were enriched in multiple hormone-related pathways, including thyroid hormone, parathyroid hormone, insulin secretion, and Cushing’s syndrome." (PMID 41388389, 2025). "In a mouse model of Cushing syndrome insulin sensitivity and metabolic parameters negatively correlated to the loss of M. gastrocnemius, not M. soleus, mass." (PMID 36988756, 2023). "The enriched pathways were associated with a series of metabolism processes, including carbohydrate digestion and absorption, adipocytokine, insulin, estrogen signaling pathways, and Cushing syndrome." (PMID 37251921, 2023). "In Cushing’s syndrome or following a two-week exposure to GC, subjects show high insulin plasma levels at a basal state, but fail to increase their insulin response to a glucose load or standardized meals." (PMID 33435513, 2021). "KEGG pathway analysis indicated that these different phosphoproteins were primarily involved in amphetamine addiction, insulin secretion, Cushing syndrome, circadian entrainment, and the Wnt signaling pathway." (PMID 34520625, 2021). "These phosphoproteins were found to be involved in many essential biological pathways, and the first five pathways included amphetamine addiction, insulin secretion, Cushing syndrome, and the circadian entrainment signaling pathway." (PMID 34520625, 2021). "Single hormone deficiency - ACTH in isolated ACTH deficiency or insulin in T1DM) are more commonly reported than single hormone excess - thyroxine in Graves’ disease and ACTH in Cushing’s syndrome." (PMID 30693099, 2019). "Two patients were excluded: one patient was diagnosed as having preclinical Cushing syndrome, and the other was excluded because of the presence of an insulin autoimmune antibody." (PMID 24684803, 2014). "Moreover, we observed more pronounced alterations in hormone-related pathways—including Cushing syndrome, aldosterone, insulin secretion, parathyroid hormone, and thyroid hormone—in patients presenting with PNS." (PMID 41388389, 2025). "The KEGG pathway enrichment analysis revealed that the genes were enriched in multiple signaling pathways related to hormone synthesis and secretion, including Cushing syndrome; insulin secretion; parathyroid hormone synthesis, secretion, and action; and thyroid hormone (P < 0.05)." (PMID 41388389, 2025). "Screening for metabolic diseases such as insulin dysregulation or Cushing’s syndrome could provide interesting information." (PMID 38829841, 2024). "The enrichment of Kyoto Encyclopedia of Genes and Genome pathways was found to be involved in many essential biological pathways, and the top five pathways included amphetamine addiction, insulin secretion, Cushing syndrome, and the circadian entrainment signaling pathway." (PMID 34520625, 2021). "Further, gene set enrichment analysis revealed the top five co-occurring molecular pathways (p ≤ 0.05) among the two sets of genes: Cushing syndrome, Axon guidance, cAMP signaling pathway, Insulin secretion, and Glutamatergic synapse, wherein all show a very close relation to synaptic plasticity." (PMID 31018568, 2019).
Cushing syndrome (continued). "Altogether, 5 out of 21 enriched pathways, namely, Cushing syndrome (p = 0.005), Axon guidance (p = 0.007), cAMP signaling pathway (p = 0.010), Insulin secretion (p = 0.016), and Glutamatergic synapse (p = 0.028) were coinciding when compared to nine commonly enriched pathways among Set A and B." (PMID 31018568, 2019). "Mares presenting Cushing’s syndrome obtained the highest (p < 0.0001) IGF-1 and glucose insulin ratio." (PMID 40901060, 2025). "Moreover, the increased insulin sensitivity in adipose tissue of Adipose-GR-KO mice treated with corticosterone, resulted in an expansion of the fat mass, protecting individuals against liver steatosis as observed in hypercorticism conditions, such as Cushing’s syndrome." (PMID 33435513, 2021). "RU486 administration improves glycemic control and insulin sensitivity in rodents given HFD for 4 weeks and lowers glycated hemoglobin levels in patients with Cushing's syndrome who often exhibit poor glycemic control." (PMID 24642683, 2014). "As a direct consequence, insulin secretion in subjects with Cushing syndrome will not suffice to adequately control plasma glucose in response to a glucose load." (PMID 35897752, 2022). "In contrast, among patients without clinically apparent PNS, only Cushing syndrome, insulin secretion, and parathyroid hormone synthesis, secretion and action showed significant changes (P < 0.05), and none remained significant after FDR correction (P.adjust > 0.3)." (PMID 41388389, 2025). "Since Cushing’s syndrome is characterized by elevated postprandial glucose levels, medications that lower these levels—such as DPPIV inhibitors, GLP1 receptor agonists, and rapid-acting insulin—may prove to be very beneficial." (PMID 36422243, 2022). "Elevated resistin levels were found in patients with Cushing’s syndrome; however, a curative surgery did not influence resistin concentration despite a fall in UFC and improved insulin sensitivity." (PMID 25129652, 2015).
liver cirrhosis (46 papers, 2006 to 2025). "published that patients with insulin‐resistant diabetes who also had liver cirrhosis and used insulin injections were associated with higher risks of death and liver‐related complications than patients with the same conditions but did not use insulin." (PMID 40022609, 2025). "Insulin was reported to be associated with a high risk of mortality in persons with T2DM; our study also showed that among persons with compensated liver cirrhosis, insulin users demonstrated a higher risk of all-cause mortality than insulin nonusers." (PMID 34118892, 2021). "BCAAs not only serve as an energy substrate in patients with liver cirrhosis but also improve liver regeneration, immune function, albumin production, ammonia metabolism, and insulin sensitivity." (PMID 39068612, 2024). "The metabolic function of hepatocytes changes in liver cirrhosis, which is characterized by insulin resistance and increased gluconeogenesis." (PMID 37886975, 2023). "We have conducted a retrospective cohort study to investigate the long-term outcomes of insulin use in persons with T2D and compensated liver cirrhosis." (PMID 35252271, 2022). "During muscle work, the glycolysis, the CAC activity, and ATP turnover in muscles increase whereas in liver cirrhosis there is a decrease due to impaired function of mitochondria and insulin resistance." (PMID 36295872, 2022). "Several structural changes in liver cirrhosis can decrease the extraction of insulin by the liver, leading to increased systemic insulin levels by a reduction in liver cell mass and/or the formation of portosystemic venous collaterals." (PMID 35836436, 2022). "In the complete cohort, a history of insulin use and liver cirrhosis, as well as mean BG and BG variability [expressed as mean absolute glucose (MAG) change], was associated with a higher mortality risk." (PMID 30742240, 2019). "Nearly all patients with liver cirrhosis are insulin resistant, β-cells respond to this resistant by increasing insulin levels (hyperinsulinaemia)." (PMID 22493645, 2009). "Combined with close titration of insulin doses and monitoring of blood glucose, insulin therapy may be a safe and effective antidiabetic management strategy in patients with decompensated liver cirrhosis." (PMID 35252271, 2022). "Different patients with liver cirrhosis require different levels of insulin." (PMID 35252271, 2022). "Decreasing the RAGE–AGE signaling by avoiding overcooked foods, sensitizing insulin function, controlling high glucose, and oxidant supplement digestion is an auguring approach to reducing the hazard of liver cirrhosis and HCC in CHC patients, particularly with raised AGEs." (PMID 34660332, 2021). "Insulin treatment and liver cirrhosis were found more frequently in the study group." (PMID 32268517, 2020). "Other described mechanisms of liver cirrhosis effect on glucose homeostasis include increased advanced glycations products, increased formation of hypoxia-inducible factors, and reduced pancreatic beta-cell function, which will lead to decreased insulin secretion." (PMID 35836436, 2022). "Therefore, in persons with compensated liver cirrhosis, the use of insulin may require special attention." (PMID 34118892, 2021). "Although insulin is the recommended treatment for persons with T2DM and liver cirrhosis, few clinical studies have evaluated its long-term effects and safety." (PMID 34118892, 2021). "Currently, there are no guidelines recommending the best insulin preparation to treat patients with T2D and liver cirrhosis." (PMID 35252271, 2022). "In the matched cohort of people with T2DM and compensated liver cirrhosis, 627 (30.63%) insulin users and 979 (23.91%) insulin nonusers died during the follow-up period (incidence rate of 5.28 vs 4.07 per 100 patient-years, respectively)." (PMID 34118892, 2021).